IL1B (interleukin 1 beta)
Diseases named in the same sentence as IL1B in open-access papers (continued):
Sharing a sentence is not in itself a finding about the gene and the disease.
chronic hepatitis B (14 papers, 2005 to 2026). "Previous studies reported that the IL-1β SNPs were linked to the development and pathogenesis of numerous chronic inflammatory diseases as well as the progression towards chronic hepatitis B." (PMID 36678401, 2022). "Furthermore, genome-wide association study in southwest China revealed 6 new loci, including the rs16944 SNP in the IL1B gene, associated with an increased prevalence rate of chronic hepatitis B." (PMID 34161370, 2021). "The mRNA and protein levels of IL‐1β were higher in patients with chronic hepatitis B than in healthy controls, and IL‐1β levels were positively correlated with disease severity." (PMID 37078407, 2023). "We have previously shown that interleukin-1beta (IL-1β) is related to the effectiveness of IFN-α treatment in chronic hepatitis B (CHB) patients." (PMID 37208599, 2023). "Very limited information exists in Thailand that reported the associations of IL-1β C-511 T and TNF-α G-308A polymorphisms with the risk of various cancers, especially in chronic hepatitis B virus infection-linked HCC." (PMID 30139338, 2018). "In this study, the expression AIM2, and its downstream cytokines, caspase-1, IL-18 and IL-1β, in liver tissue of patients with chronic hepatitis B and C (CHB, CHC) were investigated." (PMID 26290184, 2015). "Interestingly, TNF-α and IL-1β, which are known to co-induce the other's expression, are both involved in chronic inflammatory diseases such as RA, chronic hepatitis B and C infection." (PMID 21858242, 2011). "IL-17A can also significantly stimulate monocytes and DCs to express their ligand (IL-17R) and produce pro-inflammatory cytokines such as IL-1β, TNF-α, IL-6, etc., which are important for liver damage during progression of chronic hepatitis B." (PMID 33435966, 2021). "Furthermore, chronic hepatitis B patients exhibited an immune response to MAG1 characterized by elevated levels of Interleukin-6 (IL-6) and interleukin-1β (IL-1β) cytokines." (PMID 41041334, 2025). "While serum IL-2r (p = 0.002), IL-6 (p = 0.001), IL-8 (p = 0.013), PTH (p = 0.029), and CTX (p = 0.021) levels were higher in children with chronic hepatitis B than in healthy controls, there was no significant different in respect to serum IL-1β, TNF-α and osteocalcin levels." (PMID 16171525, 2005).
Huntington disease (14 papers, 2010 to 2026). Huntington disease (HD) is a rare neurodegenerative disorder of the central nervous system characterized by unwanted choreatic movements, behavioral and psychiatric disturbances and dementia. "Aberrant RIP2 activity has been implicated as a driver of inflammation in diseases such as Huntington’s Disease, where it causes increased caspase-1 activation and IL-1β production, ultimately leading to neuronal cell death." (PMID 39483336, 2024). "Additionally, loss of IL-1β signaling exacerbated motor deficits and increased the levels of mutant huntingtin in the striatum of the N171-82Q Huntington’s disease (HD) mouse." (PMID 30044427, 2018). "To evaluate whether cytokines are altered in peripheral blood of rats transgenic for the human Huntington ́s disease mutation we investigated serum levels of GRO/KC, IL-1β, IL-13 and TNF-α at a symptomatic stage at 12 months of age." (PMID 20981129, 2010).
intestinal infection (14 papers, 2013 to 2025). "Acute gastrointestinal infection with intracellular pathogens like Salmonella Typhimurium triggers the release of the proinflammatory cytokine interleukin 1β (IL-1β)." (PMID 38236896, 2024). "Gastrointestinal infections may upregulate IL-6 and IL-1β genes, therefore enhancing the permeability of the gastrointestinal epithelial cells." (PMID 41383965, 2025). "The IL-1β secretion, which controls the innate cytokines IL-25 and IL-33 production, both critical for the Th2 promotion, has been proposed as a mechanism to assure the chronicity of the parasite in intestinal infections by nematodes." (PMID 30967874, 2019). "Finally, we also demonstrated that P17-treated mice infected with C. albicans develop less severe gastrointestinal infection related to a higher efficiency of their macrophages to engulf Candida, to produce ROS and IL-1β and to kill the yeasts." (PMID 29250064, 2017). "Indeed, P17-treated mice infected with C. albicans develop less severe gastrointestinal infection related to a higher ability of their macrophages to engulf Candida, to produce ROS, IL-1β, and to kill C. albicans as compared to untreated mice." (PMID 29250064, 2017). "Many studies have shown that Th1 cytokines, such as IL-12, INF-γ, IL-1β, and TNF-α are much more abundant in the early stages of intestinal infection by T. spiralis." (PMID 38166140, 2024). "In the situation of intestinal infection, JNK inhibition resulted in reductions of c-Jun expression and significant suppression of proinflammatory cytokines such as IL-1β, IL-6, and TNF-α." (PMID 33281910, 2020). "Soon after intestinal infection S. enterica induces a significant increase in the expression of IL-17 and related cytokines such as TNF-α, IL-1β, IL-6 and IL-23." (PMID 24340048, 2013). "Altogether, the simultaneous release of IL-1β and Stx2-dependent cell death triggered by EHEC strain is a very inflammatory condition that could influence the outcome of intestinal infections." (PMID 31947665, 2020).
necrotizing enterocolitis (14 papers, 2017 to 2026). Necrotizing enterocolitis (NEC) is a devastating disease that affects mostly the intestine of premature infants. "IL-1β was upregulated significantly in SIGIRR-deficient mice with necrotizing enterocolitis." (PMID 31684202, 2019). "Recent research has also shown that SFN (20 mg/kg/day) mitigates necrotizing enterocolitis (NEC) by reducing the expression of IL-1β, IL-8, IL-10, IL-6, and TNF-α, thereby decreasing apoptosis in NEC-induced mice." (PMID 38671854, 2024).
neutropenia (14 papers, 2013 to 2025). A decrease in the number of neutrophils found in the blood. "TGF-β and IL-1β have the capacity to instruct naive T cells to develop into IL-17-producing Th17 cells which trigger inflammatory responses, including neutropenia, tissue remodeling, and the production of antimicrobial proteins." (PMID 36553455, 2022). "The absence of an effect on IL1β expression in the present study following neutropenia, RAG1 deficiency, or AT1 inhibition may be attributed to low levels of cytokine mRNA at 3 days post CCI15." (PMID 37150755, 2023). "The concentrations of tumor necrosis factor-α, interleukin (IL)-1β, IL-6 and myeloperoxidase in BAL fluid were significantly inhibited by imatinib or nilotinib in mice of ALI during neutropenia recovery." (PMID 23787115, 2013). "In mice, IL1β-dependent G-CSF production is required for early HSC expansion during emergency granulopoiesis, and G-CSF (but not IL1β) is required for neutrophil homeostasis at steady state after induction of neutropenia with Ly6G antibody." (PMID 38992437, 2024). "Compared with naive brain, SAH induction in the absence of neutropenia significantly enhanced the tissue expression of all three inflammation markers (IL-1β: 477 ± 99%; TNFα: 3978 ± 318%; iNOS: 150 ± 17%)." (PMID 31186479, 2019).
otitis media (14 papers, 2009 to 2025). Inflammation of the anatomical structures of the middle ear, which is most often caused by an infectious process. "The presence of IL-1β or the presence of otitis media is associated with higher MUC8 concentrations and a higher density of ciliary-bearing cells in the epithelium." (PMID 34943565, 2021). "Pro-inflammatory cytokines like IL-1β and IL-6 have a significant involvement in otitis media development and its progression." (PMID 40895301, 2025). "Regarding the potential role of inflammasomes in middle ear diseases, one experimental animal study revealed aberrant overexpression of NLRP3, ASC, caspase-1, and IL-1β in lipopolysaccharide-induced otitis media." (PMID 34805037, 2021). "Inflammatory cytokines such as IL1α, IL1β, and tumor necrosis factor produced by macrophages and monocytes in response to microbial toxin play a vital role in middle ear inflammation and OM." (PMID 32391052, 2020). "This indicated that the TNF-α, IL-1β, IL-6, IL-8 and IL-10 involved into inflammatory response in otitis media." (PMID 22173336, 2011). "Additionally, pranlukast (another LT receptor antagonist) alleviated otitis media with its anti-inflammatory action as it decreased the levels of IL-1β." (PMID 37396939, 2023). "However, Leffers, in his article on the immunomodulatory response of epithelial cells in otitis media, evaluated the immunohistochemical changes that occur in the epithelium after inoculation with Haemophilus influenzae, finding an increase in IL-1β, IL-6, IL-8, and TNFα." (PMID 40559231, 2025). "A histopathological analysis confirmed that treatment with the nanocarriers reduced the levels of pro-inflammatory cytokines (IL-1β, TNF-α, TLR4, IL-6) and raised the levels of antioxidant markers (Nrf-2, SOD) in an in vivo rat model of otitis media." (PMID 40143156, 2025). "In vivo experiments utilizing a rat model of otitis media demonstrated a significant reduction in the levels of pro-inflammatory cytokines TNF-α, IL-1β, TLR4, and IL-6, and greater levels of Nrf-2 and SOD in comparison to untreated controls." (PMID 40143156, 2025). "Otitis media are accompanied by raised expression of vascular endothelial growth factor, TNF-α and IL-1β in ear fluids, during which TGIF1 mutants illustrate auditory deficits." (PMID 33414721, 2020).
reflux esophagitis (14 papers, 2014 to 2025). "Similarly, Taiwanese carriers of the IL-1B-511 T allele have an increased risk of reflux esophagitis." (PMID 36838318, 2023). "However, other investigators have reported contradictory results that IL-1B-511-T allele was associated with reflux esophagitis." (PMID 25642246, 2015). "Studies performed in a mouse model of gastroesophageal reflux showed upregulation of inflammatory-related genes, especially NF-κB target genes (matrix metalloproteinases-3 and -9, IL-1β, IL-6, and IL-8)." (PMID 33941087, 2021). "And it also shows its therapeutic effect on gastroesophageal reflux disease rats by reducing the levels of pro-inflammatory biomarkers such as IL-1β, IL-6 and TNF-α." (PMID 33841162, 2021). "Previous research has demonstrated that the TNF-α, IL-1β, and IL-6 concentrations increased in the esophageal tissues of rats in several reflux esophagitis models." (PMID 31281769, 2019). "The expression level of interleukin-1β (IL-1β) in reflux esophagitis was significantly higher than the control in all phases examined." (PMID 28757556, 2017). "Patients with reflux esophagitis have high levels of IL-8 and IL-1β and patients with adenocarcinoma show markedly elevated levels of IL-8 and IL-1β." (PMID 25276052, 2014). "Study demonstrated that enriched genes including IL1B, CXCR1, FFAR4, VIP (vasoactive intestinal peptide), and GATA3 have been identified as a key candidate genes in patients with gastroesophageal reflux disease." (PMID 38137330, 2023). "However, how these markers are correlated to DIS still needs further investigation because DIS and basal hyperplasia were reported to be related to IL-1β or IL-8 levels, which were not upregulated in the heartburn patients in this study." (PMID 27111066, 2016).
SARS-CoV infection (14 papers, 2008 to 2023). "There is other mechanism of infection related to SARS-CoV infection which is associated with high levels of cytokines, including interleukin (IL)-1β, IL-6, IL-12, interferon gamma (INFγ) and tumor necrosis factor-alpha (TNFα)." (PMID 33613024, 2021). "The levels of active IL-1β secreted to the airways were enhanced when E protein IC activity was conserved in SARS-CoV infection." (PMID 24788150, 2014). "In the present study, a sum of three polymorphisms (SQSTM1 rs10277, IL1B rs1143627, EGFR rs712829) of 2-DG interacting genes may increase the susceptibility to SARS-CoV infections than other polymorphisms." (PMID 36164436, 2022). "Our studies indicate that protection from SARS-CoV infection correlates with MyD88-dependent induction of IL1-β, TNF-α, IL-6, MCP-1, MIP-1α, and RANTES at early times post infection and many of these cytokines/chemokines were upregulated in human SARS-CoV cases." (PMID 19079579, 2008). "Thus, similar to SARS-CoV infection, SARS-CoV-2 infection increases the secretion of interleukin 1 beta (IL-1β), interferon-c (IFN-c), human interferon-inducible protein 10 (IP-10), monocyte chemoattractant protein-1 (MCP-1), IL-4, and IL-10." (PMID 37654997, 2023). "In view of the large amounts of cytokines produced during SARS-CoV infection, infection with SARS-CoV-2 similarly induces the production of proinflammatory cytokines such as, interleukin 1 beta (IL-1β), interferon gamma (IFN-γ), IP10 and monocyte chemoattractant protein 1 (MCP)." (PMID 32524843, 2020). "Lack of ion exchange through the E protein following SARS-CoV infection results in lower levels of IL-1β and lower immune-related pathology." (PMID 33149733, 2020).
schistosomiasis (14 papers, 2011 to 2025). An infectious disease caused by parasitic trematodes of the genus Schistosoma that colonize human blood vessels and release eggs that can cause granulomatous reactions leading to acute (swimmer's itch or acute schistosomiasis syndrome) or chronic disease. "IL-1β is a significant mediator of tissue damage and plays an essential role in the progression of schistosomiasis." (PMID 39439825, 2024). "Cytokines such as TNF-α, IL-1β, IL-6, IL-4, and IL-10, among others, show increased serum levels during schistosomiasis, reflecting the polarization and complexity between Th1 and Th2 immune responses." (PMID 38239348, 2023). "IL-23 and IL-1β are key factors involved in the generation of antigen-specific Th17 cells in the pathogenesis of severe schistosomiasis." (PMID 37887717, 2023). "In schistosomiasis, IL-23 and IL-1β are necessary for IL-17 production in response to parasite eggs and severe immunopathology correlates with increased production of IL-17." (PMID 21998578, 2011). "Also, the injection of GNPs into schistosomiasis-infected mice resulted in a significant downregulation of IL-1β and TNF-α expressions in the hepatic tissue of mice, thus improving liver dysfunction." (PMID 34944582, 2021). "Pretreatment of NLRP3−/− and AIM2−/− BMDCs with IFN-I receptor blocking antibody led to a marked increase in IL-1β and IL-17 production, demonstrating a novel mechanism by which IFN-I signaling regulates inflammation in schistosomiasis." (PMID 38559160, 2024). "Current data using mesenteric endothelial cells primed by schistosomiasis unveiled positive cooperation between P2Y2R and P2X7R signaling, increasing IL-1β release, VCAM-1 expression, and monocyte adhesion." (PMID 38239348, 2023). "Quantification of inflammatory mediators in liver fragments from a chronic model of schistosomiasis showed a significant decrease in TNF-α, IL-1β (P < 0.01) and IL-6 (P < 0.001) levels after cell therapy." (PMID 31015492, 2019).
systemic sclerosis (14 papers, 2013 to 2025). A chronic disorder, possibly autoimmune, marked by excessive production of collagen which results in hardening and thickening of body tissues. "To reach this objective, we evaluated the presence of caspase-1, lactate dehydrogenase (LDH), the cytokines IL-1β and IL-18, and the association between them in the bronchoalveolar lavage (BAL) of patients with ASSD and systemic sclerosis (SSc)." (PMID 36611853, 2022). "In an Iranian study, the authors reported that some haplotypes of SNPs IL-1A rs1800587, IL-1B rs1143634 and IL1R1 rs2234650 were associated with systemic sclerosis." (PMID 32252823, 2020). "In addition to these findings, our results demonstrate significant overlap between IL-1B/IL-36 increased DEGs and genes linked by GWA studies to systemic sclerosis and primary biliary cholangitis." (PMID 29434599, 2018). "Similarly, fibrotic patients display elevated IL-1β levels, and systemic sclerosis patients produce considerably higher amounts of extracellular matrix upon exposure to IL-1β." (PMID 24367371, 2013). "For instance, in dermal fibroblasts from patients with systemic sclerosis, the inhibition of CASP1 reduces the collagen deposition and the IL-18 and IL-1β release." (PMID 38786058, 2024).
vitamin D deficiency (14 papers, 2014 to 2025). A nutritional condition produced by a deficiency of VITAMIN D in the diet, insufficient production of vitamin D in the skin, inadequate absorption of vitamin D from the diet, or abnormal conversion of vitamin D to its bioactive metabolites. "Vitamin D deficiency has been linked to enhanced expression of proinflammatory interleukins such as IL-1β, IL-6, and TNF-α, which are physiological mediators of the inflammatory response and are frequently elevated in the tears of DES patients." (PMID 41157226, 2025). "In patients with vitamin D deficiency, the increases in IL-6 and caspase-3 expression, alongside elevated levels of IL-1β and CXCL10, emphasize a pronounced inflammatory and apoptotic milieu." (PMID 39062991, 2024). "The relationship between vitamin D deficiency and levels of IL-1β, IL-4, and IL-6 was previously shown in obese rats fed a vitamin D-reduced high-fat diet." (PMID 39310506, 2024). "Significantly decreased adropin levels and significantly increased levels of proinflammatory cytokines (IL-1β, IL-6) were detected in vitamin D deficiency with the oxidative/antioxidative balance being changed in favor of oxidative status." (PMID 36326375, 2022). "Elevated TNF-α, INF-γ, IL-1β, and IL-2 levels have been observed in patients with vitamin D deficiency." (PMID 34281061, 2021). "The present study showed that vitamin D deficiency elevated the alcohol-induced increase of hepatic tnf-α, il-1β, kc, and mcp-1 mRNA expressions." (PMID 32184917, 2020). "Vitamin D deficiency significantly elevated alcohol-induced upregulation of hepatic tnf-α and il-1β mRNAs." (PMID 32184917, 2020). "We aimed to evaluate the relationship between the levels of vitamin D and adropin, IL-1β, IL-6 and oxidative status, which, we think might affect the pathological and metabolic conditions seen in vitamin D deficiency." (PMID 36326375, 2022). "Clinical and animal studies have suggested that vitamin D deficiency may be associated with increased circulating IL-1β and TNFα as well as with increased fibroblast proliferative activity." (PMID 30273386, 2018). "By detecting liver inflammation level, we found that IL-1β, IL-6and TNF-α were significantly elevated in livers and pancreas of the offspring in the vitamin D deficiency group compared to control group at all time points." (PMID 32184720, 2020). "But vitamin D deficiency is associated with an exacerbation of Th1 immune response, resulting in the upregulation of the expression and production of several proinflammatory cytokines including TNF-α, IL-1β, IL-6, and IL-8, too." (PMID 29200598, 2017). "Vitamin D deficiency significantly enhanced the basal expression of IL-1β, IL-6, and TNF-α in the lungs of mice, while did not influence the basal expression of CXCL1 and CCL3." (PMID 24926881, 2014).